RBM15B (RNA binding motif protein 15B)
Diseases named in the same sentence as RBM15B in open-access papers (continued):
Sharing a sentence is not in itself a finding about the gene and the disease.
head and neck cancer (1 paper, 2021). A primary or metastatic malignant neoplasm affecting the head and neck. "It was found that head and neck cancer samples with high expression of writer genes KIAA1429 were in positive correlation with eraser genes ALKBH3 and FTO, while tumors with a high expression of writer genes (RBM15, RBM15B, and CBLL1) exhibited a low expression of eraser genes (ALKBH3 and FTO)." (PMID 35198565, 2021).
Obesity (1 paper, 2022). Accumulation of substantial excess body fat. "In contrast, METTL15, zinc finger CCCH-type containing 13 (ZC3H13), fat mass and obesity-associated (FTO), leucine-rich pentatricopeptide repeat containing (LRPPRC), and RNA-binding motif protein 15B (RBM15B) showed widespread CNV frequency loss." (PMID 34979500, 2022).
osteomyelitis (1 paper, 2022). An acute or chronic inflammation of the bone and its structures due to infection with pyogenic bacteria. "In the m6A regulators-associated molecular subtypes, METTL3, CBLL1 and LRPPRC were significantly more highly expressed in subgroup A osteomyelitis than in subgroup B, while RBM15B and YTHDC1 expression were higher in subgroup A osteomyelitis." (PMID 36544487, 2022). "Visualization of the results by boxplot and heatmap suggested that the 5 regulators were differentially expressed between the two m6A subtypes, with METTL3, CBLL1 and LRPPRC highly expressed in cluster A osteomyelitis, RBM15B and YTHDC1 highly expressed in cluster B osteomyelitis." (PMID 36544487, 2022). "The qRT‒PCR results showed that the mRNA expression of METTL3, YTHDC1, RBM15B, LRPPRC and CBLL1 in osteomyelitis tissues was significantly increased, while that of YTHDF2 was significantly decreased (p < 0.05), which was consistent with the results of bioinformatics analysis." (PMID 36544487, 2022). "Based on the 6 significant m6A regulators with differential expression in the dataset, we further validated the expression of the 6 m6A regulators (METTL3, YTHDC1, YTHDF2, RBM15B, LRPPRC and CBLL1) in 10 osteomyelitis samples and 10 control samples by qRT‒PCR analysis." (PMID 36544487, 2022).
osteoporosis (1 paper, 2023). A condition of reduced bone mass, with decreased cortical thickness and a decrease in the number and size of the trabeculae of cancellous bone (but normal chemical composition), resulting in increased fracture incidence. "In addition, study has reported that knockdown of RBM15 and RBM15B impairs XIST-mediated gene silencing, which influences osteoblast differentiation in osteoporosis." (PMID 36967763, 2023).
prostate tumors (1 paper, 2021). "Seven regulators, including IGF2BP2, METTL3, METTL16, ZNF217, ZC3H13, RBM15B, and PRRC2A, exhibited significant correlations between CNVs and gene expression levels in prostate tumors." (PMID 34899855, 2021).
pulpitis (1 paper, 2023). Inflammation of the dental pulp. "The results showed that there were significant differences in the genes ALKBH5, METTL14, METTL3, METTL16, RBM15B and YTHDF1 between normal group and the pulpitis group." (PMID 37978362, 2023). "However, YTHDF1, YTHDF3, METTL16 and METTL3 gene expression were not statistically different between the pulpitis group and the control group, and RBM15B, ZCCHC4 and ALKBH5 were up-regulated." (PMID 37978362, 2023).
respiratory allergy (1 paper, 2023). "Therefore, we hypothesized that the expression of METTL14, METTL16, and RBM15B closely influences the pathogenesis of respiratory allergies in mast and Th2 cells." (PMID 37328853, 2023). "Another example is Th2 cells, whose hyperactivation is key to respiratory allergy, whereas the number of Th2 cells was negatively correlated with METTL16 expression and positively correlated with RBM15B expression in our results." (PMID 37328853, 2023).
Sepsis (1 paper, 2023). Sepsis is defined as life-threatening organ dysfunction caused by a dysregulated host response to infection. "In this predictive nomogram, the expression levels of FTO, HNRNPC, RBMX, YTHDC1, LRPPRC, and RBM15B were negatively associated with the risk score of patients with sepsis and were regarded as protective factors in sepsis." (PMID 36781867, 2023).
tumor (41 papers, 2018 to 2026). "Overexpression of TRAM2 attenuated the reduction in subcutaneous tumor volume in nude mice caused by knockdown of RBM15B." (PMID 35494016, 2022). "In TCGA cohort, the expression levels of LRPPRC and RBM15B and the m6A risk score were significantly correlated with tumour grade and T stage." (PMID 34512165, 2021). "Only RBM15B expression levels and the m6A risk model score were associated with tumour stage and T stage." (PMID 34512165, 2021). "Additionally, KIAA1429, LRPPRC, and RBM15B and the m6A risk scores were significantly different between different tumour stages." (PMID 34512165, 2021). "Compared with normal counterparts, 4 DEMGs (FTO, ZC3H13, METTL14 and RBM15B) were significantly down-regulated in tumor samples, while the remaining 11 genes were upregulated in tumor samples." (PMID 36536402, 2022). "We found that KIAA1429, ZC3H13, and RBM15B presented the highest CNV frequency, and ZC3H13 exhibited a loss in copy number, which corresponded to the expression level of ZC3H13 in tumor samples." (PMID 34733275, 2021). "In the ICGC cohort, KIAA1429, LRPPRC, RBM15B, and YTHDF2 expression levels and the m6A risk score were significantly correlated with tumour grade." (PMID 34512165, 2021). "The results showed that ELAVL1, YTHDF2, RBM15, HNRNPA2B1, ALKBH5A, and RBM15B expression was significantly upregulated in tumor tissues compared with normal tissues (p < 0.05)." (PMID 34900988, 2021). "Since the expression levels of the four selected genes (KIAA1429, LRPPRC, RBM15B, and YTHDF2) play a crucial role in tumorigenesis and tumour development, we employed them to establish an m6A risk signature model." (PMID 34512165, 2021). "The AUC of the m6A risk model in 1/2/3 years was better than that of the expression of other genes (KIAA1429, YTHDF2, and RBM15B) and other factors, such as age, sex, and tumour grade." (PMID 34512165, 2021). "RBM15B, located in close proximity to the 3p21 tumour suppressor region, is highly positively correlated with BRCA1-associated protein-1 expression in both black and white female patients with invasive breast carcinoma." (PMID 34044876, 2021). "Correlation between clinicopathological features and RBM15B expression in HCC tumor tissues." (PMID 35494016, 2022). "Moreover, the TCGA database and the Cancer Cell Line Encyclopedia (CCLE) database showed that RBM15B was overexpressed in most tumor tissues and cell lines." (PMID 35494016, 2022). "Our results showed that knocking down RBM15B inhibited tumor growth in vivo." (PMID 35494016, 2022). "The results revealed that IGF2BP3, RBM15B, and METTL16 mutations may be potential biomarkers for certain anti-tumor therapies." (PMID 34446007, 2021). "A RBM15B has lower expression in tumor tissues and B lower expression could result in a worse OS, and C has a positive correlation with P2RX6 expression in TCGA database." (PMID 31159832, 2019). "For instance, in TGCTs, higher VIRMA expression was found to be associated with low disease stage; in addition, in KCa, RBM15B overexpression (an eraser) associated with advanced disease at diagnosis, whereas the writer METTL3 was reported to act as a tumor suppressor." (PMID 30428628, 2018). "That is, RBM15B may suppress tumour growth in these breast patients." (PMID 34044876, 2021). "However, RBM15B has lower expression in tumor tissues and lower expression could result in worse OS, also RBM15B has a positive correlation with P2RX6 expression in TCGA database." (PMID 31159832, 2019). "RESULTS: RBM15B was highly expressed in GBM, and RBM15B downregulation suppressed GBM cell proliferation, migration, invasion, and tumor growth." (PMID 42020859, 2026). "Specifically, the m6A writers METTL3, WTAP, and RBM15B and the m6A readers YTHDF1 and HNRNAPA2B1 showed significant upregulation in the high PCa tumor grades compared to the low tumor grades and adjacent normal tissues." (PMID 38610981, 2024).
tumor (continued). "Particularly, m6A writers showed high up-regulated expression in tumor samples, such as METTL3, RBM15, RBM15B and WTAP." (PMID 35847857, 2022). "We found that METTL3, RBM15B, YTHDC2, YTHDF2, and HNRNPA2B1 were indeed highly expressed in the tumor samples." (PMID 34336856, 2021). "On the contrary, METTL3, KIAA1429, RBM15B, HNRNPA2B1, and HNRNPC had significantly higher expression in tumor tissues (p < 0.001)." (PMID 34277622, 2021). "Our data show that seven m6A regulators (CBLL1, ELAVL1, LRPPRC, RBM15B, YTHDF1, YTHDF2, and ZC3H13) are related to tumorigenesis, tumor microenvironment and tumor prognosis." (PMID 33670062, 2021). "We found that METTL14 and RBM15B mRNA expression significantly decreased, while FTO significantly increased in tumor tissues." (PMID 31159832, 2019). "Our study showed for the first time that RBM15B could predict a poor prognosis in HCC patients and was significantly related to tumor size, TNM stage and PVTT stage." (PMID 35494016, 2022). "The overexpression of RBM15B, METTL14, and HNRNPA2B1 is significantly related to tumor metastasis." (PMID 32582536, 2020). "The role of genes RBM15B and USP19 may be important in BAP1 function and give further insight into the mechanism of BAP1 tumor suppression and additional targets for therapy." (PMID 30716094, 2019). "Furthermore, UALCAN revealed that the gene expression differences in METTL3, RBM15, RBM15B, VIRMA and CBLL1 may also be related to tumor grade." (PMID 35223847, 2022).
cancer (25 papers, 2019 to 2026). A tumor composed of atypical neoplastic, often pleomorphic cells that invade other tissues. "Notably, RBM15B with loss of copy numbers still expressed higher in cancer samples." (PMID 35449086, 2022). "The oncogenic role of m6A writer RNA-binding motif protein 15B (RBM15B) has been confirmed in multiple cancers." (PMID 42020859, 2026). "High expression levels of RBPs, such as RBM15B, have also been associated with poor prognosis in patients with HCC and the promotion of cancer cell proliferation and invasion." (PMID 38305811, 2024). "Of them, TARBP1, KIAA1429, MTEEL3, RBM15, RBM15B, and TARBP1 had extensive somatic mutation among pan-cancers." (PMID 36707911, 2023). "GSEA demonstrated the enrichment of pathways related to cancer between the RBM15B high and the low groups." (PMID 35494016, 2022). "Emerging evidence implicates RBM15B plays an important part in carcinoma growth and metastasis in several cancers." (PMID 36003405, 2022). "RBM15B, a component of the m6A writer complex, shows cancer-type specific functions." (PMID 40565233, 2025). "Moreover, significantly different RBM15B expression was observed in subgroups of patients’ age and cancer stages based on the UALCAN database." (PMID 36003405, 2022). "High RBM15B levels are correlated with multiple immune signatures and cancer-related pathways." (PMID 34976022, 2021). "Kyoto Encyclopedia of Genes and Genomes (KEGG) analysis showed that RBM15B was significantly related to the “Hippo signaling pathway” and the “mRNA surveillance pathway”, indicating that RBM15B might bind specific Hippo signaling pathway-related mRNAs to exert a cancer-promoting effect." (PMID 35494016, 2022). "Our results showed that RBM15 and RBM15B were significantly up-regulated in NSCLC samples and had frequent CNV alterations, indicating their potential role in promoting cancer cell migration and invasion." (PMID 36591468, 2022). "Using the four-gene signature (YTHDF3, RBM15B, IGF2BP2, and TRMT61A), we constructed a nomogram to estimate 1-year and 3-year overall survival probabilities in patients from the eight selected TCGA cancer types." (PMID 40565233, 2025). "RBM15B and TIPIN showed significant differences in the stages of cancer development." (PMID 35082931, 2022). "Our results revealed that in GBM cancer cells, expression of CD274 (PD-L1), PDCD1LG2 (PD-L2), LGALS9 (Galectin-9), and PVR (CD155) were positively correlated with the expression of multiple m6A regulators, especially YTHDF2, YTHDF3, LRPPRC, METTL3, RBM15B, FTO, and ALKBH5." (PMID 35558067, 2022). "RBM15B was enriched in aminoacyl tRNA biosynthesis (NES = 2.12, p = 0.011), mTOR signaling pathway (NES = 1.94, p = 0.023), Notch signaling pathway (NES = 2.10, p = 0.008), pathways in cancer (NES = 1.82, p = 0.049), and Wnt signaling pathway (NES = 1.86, p = 0.044)." (PMID 33362863, 2020).
hematological malignancies (1 paper, 2026). "This study uncovers a novel selective m6A deposition mechanism mediated by H3K79me2 and RBM15B, highlighting promising therapeutic targets for hematological malignancies." (PMID 41629530, 2026).
RBM15B also shares sentences with these, for which no sentence is quoted: colon cancer (3 papers); periodontitis (2); autoimmune disease (1); bladder cancer (1); cardiovascular disease (1); cognitive deficits (1); diabetes mellitus (1); End-Stage Renal Failure (1); gastric cancer (1); glioblastoma (1); head and neck squamous cell carcinoma (1); inflammatory bowel disease (1); leukemia (1); lung squamous cell carcinoma (1); memory impairment (1); psoriasis (1); renal clear cell carcinoma (1); sarcoma (1).